HK2 (hexokinase 2)
Diseases named in the same sentence as HK2 in open-access papers (continued):
Sharing a sentence is not in itself a finding about the gene and the disease.
cancer (continued). "The clinical applicability of HK2 inhibition in cancer may be significantly limited by any potential negative effects of HK2 inhibition on T cells." (PMID 30140438, 2018). "Cancer subtypes with differential HK1/HK2 expression have not been characterized." (PMID 29988332, 2018). "Furthermore, HIF-1α has been demonstrated to act as a key regulator in glycolysis, HIF-1α is the best-known transcriptional regulators controlling expression of glycolysis genes, such as HK1, HK2, and LDHA, whose expression levels are highly elevated in cancer cells." (PMID 29137372, 2017). "The expression of AKT2, AKT3, PKM2 and HK2 were significantly lower in the miR-29b agomir group compared with the NC agomir group, suggesting that miR-29b agomir treatment down-regulated in vivo AKT2/3 levels and further inhibited cancer cell glycolysis via downregulation of PKM2 and HK2 expression." (PMID 26512921, 2015). "HK1 and HK2 are more tightly bound to VDAC in cancer cells than in nonmalignant cells." (PMID 24648844, 2014). "Moreover, in cancer cells, the overexpression of HK2 directly regulated glycolytic activity, increasing lactate production which, in turn, promoted VEGF-A signaling, one of the pathways involved in invasion, cancer cell extravasation and colonization at distant organs." (PMID 33804240, 2021). "The lack of correlation between E6/E7 and HK2 expression in the context of HPV-positive cancer cells, however, does not preclude that E6/E7 may stimulate HK2 expression at some step of the life cycle of HPVs which is closely linked to the differentiation status of the infected keratinocyte." (PMID 29290953, 2017). "However, HK2 levels in most HPV-positive cancer cell lines are not maintained by the viral oncogenes and the anti-tumorigenic effects observed upon E6/E7 inhibition in these cells are likely not due to decreased HK2 expression." (PMID 29290953, 2017). "Given the importance of GLUT1 and HK2 in reprogramming of glucose metabolism in cancer cells, we hypothesized that aberrant expression of FOXM1 in EOC cells could also promote reprogramming of glucose metabolism, one of the hallmarks of cancer, to facilitate cancer proliferation." (PMID 27351131, 2016). "Genes like PGK1, PFKP, HK2, and LDHA, that are involved in metabolic reprogramming of cancer cells by enhancing glycolysis have a negative correlation with PEBP1/STK11 co-expression." (PMID 40806276, 2025). "Strikingly, exposure with the conditioned medium (CM) from cancer cells did not affect the glucose uptake in NSCLC/HCC-derived NPC, while it increased the expression of HK2, ROCK2, and p-MLC2 as well as lactate production in NPC as compared with untreated NPC." (PMID 34650057, 2021). "While HK2 is highly expressed in the majority of cancers, cancer subtypes with differential HK1 and HK2 expression have not been characterized for their sensitivities to HK2 silencing." (PMID 29988332, 2018). "Hexokinase 2 (HK2), which is not expressed in most mammalian tissues, is markedly induced in cancer cells by different mechanisms." (PMID 29687779, 2018). "We have studied HK2 knockdown in a large panel of naturally existing HK1+HK2+ and HK1−HK2+ cancer cells and found that only HK1−HK2+ cancer cells but not HK1+HK2+ cells as defined by mRNA and Western blot analyses are sensitive to HK2 knockdown." (PMID 29988332, 2018). "In vitro studies demonstrated that VDA-1102 selectively detaches HK2, but not HK1, from VDAC1 leading to cancer cell apoptosis as well as glycolysis inhibition and reduction in lactate secretion, culminating in proliferation inhibition." (PMID 30400835, 2018). "The expression and enzyme activity of HK2 in CD133+ stem and CD133- nonstem cancer cells have been compared." (PMID 28009990, 2017). "Participants diagnosed with cancer had higher levels of total PSA and hK2 compared with men who were not diagnosed with cancer." (PMID 18611265, 2008).
infection (59 papers, 2010 to 2025). The state of being infected such as from the introduction of a foreign agent such as serum, vaccine, antigenic substance or organism. "In our initial evaluation of the effect of HRV-C15 infection on six metabolic-associated genes, we found that levels of HK2 (HK2) and PPARGC1A (PGC-1α) were most altered during HRV-C15 infection." (PMID 34135327, 2021). "The observation that the hk2 mutant showed different infection outcomes between needle inoculation vs. tick bite underlines the importance of using nature route of tick infestation for assessment of infectivity of a B. burgdorferi mutant." (PMID 33195322, 2020). "Chemical inhibition of CDK8 and CDK19 with Senexin A during infection blocks virus-induced expression of select metabolic and autophagic genes, hexokinase 2 (HK2) and microtubule-associated protein 1 light chain 3 (LC3), and reduces viral genome replication and infectious particle production." (PMID 32560467, 2020). "However, hexokinase 2-deficient cells were also protected against apoptosis by the infection." (PMID 35397654, 2022). "We found that genes associated with glycolysis and the downstream generation of lactate (Hk2, Ldha) were upregulated during infection, across all preadipocyte populations." (PMID 37923768, 2023). "An impact on cellular metabolism is for example described for the related Dengue virus: the infection of human foreskin fibroblasts results in an increase in glucose transporter protein levels and in hexokinase 2 mRNA and protein levels." (PMID 35186796, 2022). "They demonstrated that following infection the abundance and activity of HK2 is regulated by HIF-1, and that HK2 dissociated from the mitochondrial membrane at low oxygen levels which was required for optimal parasite replication." (PMID 35646724, 2022). "Because HRV-C15 downregulates PGC-1α by 8–12 h post infection, we investigated the effect of oligomycin A on the expression of either HK2 or PPARGC1A and observed that it markedly increases PPARGC1A expression." (PMID 34135327, 2021). "Expression of Hk2 was 1.6-fold higher in uninfected Sirt3−/− BMDM compared to WT and was not further increased by M. tuberculosis, suggesting that the infection-induced increase of Hk2 in WT macrophages resulted from SIRT3 downregulation." (PMID 33531400, 2021). "Along with downregulation of TCA and ETC components, we observed SIRT3-dependent upregulation of Hk2 and Glut1 and increased lactate secretion following infection, indicating a shift toward glycolysis." (PMID 33531400, 2021). "As with Senexin A treatment, Senexin B inhibited the induction of HK2 during DENV2 infection, while basal expression of HK2 was unaffected (DMSO mean fold change over mock: 4.64 ± 0.45, Senexin B: 3.22 ± 0.45)." (PMID 32560467, 2020). "In this study, we further investigated the hk2 mutant phenotype in the tick phase of the enzootic cycle, showing that the hk2 mutant had a reduced infection via tick infestation." (PMID 33195322, 2020). "As expected, the outcome of the Senexin A block of HK2 and LC3 induction in DENV2-infected cells was loss of the increased mitochondrial respiration associated with infection." (PMID 32560467, 2020). "Tightly controlled hk2 expression is also important for mammalian infection, as HK2 overexpression led to reduced infectivity in mice." (PMID 33195322, 2020). "We measured HK2 mRNA expression during the time course of synchronized DENV2 infections and confirmed that it is upregulated compared to mock-infected cells and cells infected with equivalent UV-inactivated DENV2." (PMID 32560467, 2020). "Transcripts for Hk1 and Gck showed little change during infection and Hk2 transcripts showed >1.5-fold induction." (PMID 26658723, 2015). "In the past few years, we and others have shown that one of the B. burgdorferi two-component signaling systems, Hk2-Rrp2, functions as a key signaling pathway that governs expression of genes necessary for mammalian host infection." (PMID 21738477, 2011).
infection (continued). "Additionally, infection with N. caninum tachyzoites promoted HK2, LDH-A, and PDK1 protein levels while increasing glucose consumption and lactate production in the in vivo and in vitro models." (PMID 40307939, 2025). "Additionally, infection with human herpesvirus 6 elevates glycolytic activity, increasing glucose uptake, hk2 and ldh-a mRNA levels, glucose consumption, and lactate production in HSB-2 cells." (PMID 40307939, 2025). "As the infection with S. mansoni induced hepatic Hk2, Pkm2, and G6pdh, we aimed to analyze whether S. mansoni eggs directly stimulate these enzymes without an immune reaction against the parasite." (PMID 39404406, 2024). "Hexokinase 2 has been suggested to be involved in protection by Ctr-infection." (PMID 35397654, 2022). "While HK2 was markedly upregulated in late infection where barrier dysfunction stems from epithelial damage and wounding, PGC-1α protein and mRNA were induced during the 4-h post-infection window of elevated oxygen consumption, high ROS activity, and intact barrier function." (PMID 34135327, 2021). "Furthermore, the invA mutant S. Typhimurium was also unable to regulate the levels of Glut1 and glycolytic enzymes HK-2 and Enolase upon infection in macrophages." (PMID 34555129, 2021). "The hk2 mutant is also capable of infecting mice upon needle infection." (PMID 33195322, 2020). "Furthermore, we demonstrated that lipocalin 2 (LCN2), which is released by neutrophils at sites of infection and inflammation is involved in HK2-driven autophagy pathway." (PMID 29285270, 2017). "Furthermore, because HK2 is the predominant isoform in insulin-sensitive tissues, its decreased level in the lungs further confirms the reduced insulin sensitivity in the lungs during infection in the adult mice." (PMID 35329973, 2022). "In addition, the contribution of Hk2 during the infectious cycle of B. burgdorferi remains unknown because the previous hk2 mutant lost an important endogenous plasmid (lp36) for mammalian infection." (PMID 20862323, 2010). "Conversely, in the NP group, only a subset of genes, including HK2, PFK, KGDH3, Scs2, Gpat4a, HADH1, GOGAT1d, ALT2, GCL3, and PAH1, were significantly upregulated upon infection." (PMID 41390792, 2025). "It is also apparent from our results that in addition to the expression of the PFKFB3 gene, infection of hSMs with the UT127 strain also induced higher levels of HIF1A, HK1, HK2, PDP1, and PDP2 genes compared with the infection with UT205." (PMID 35163725, 2022). "The effect of infection on the rise of the mRNA levels of all four glycolytic genes was higher than MDI, when already by 2 dpi approximately 10-fold higher levels of Hk-2 and PFk-2 were measured, and all four mRNA increased between 15- and 150-fold by 6 dpi." (PMID 36237435, 2022). "The results showed that knock down of HK2, PDHX, and GLUT1 significantly inhibited SGIV infection, demonstrated by the marked reduction in both transcription and protein expression of SGIV MCP." (PMID 35432224, 2022). "HHV-6A infection strongly induced the protein levels of HK2, PFK1, and LDHα in HSB-2 cells compared with the mock-infected cells at 48 and 72 h post-infection." (PMID 32516328, 2020). "Gene expression analysis using a more detailed time course of infection demonstrated that induction of glycolytic genes such as GLUT1, hexokinase 2 (HK2), and PFKFB3 initiated early after the challenge, and was sustained throughout infection." (PMID 32385235, 2020). "Infection of a variety of cell lines with EBV resulted in increased expression of GLUT1, GLUT4, and HK2 that also increased glycolysis." (PMID 29518929, 2018). "The investigation of glycolytic enzymes demonstrated activation-dependent expression of hexokinases HK1 and HK2 in human CD4+ T cells, and a highly significant increase in cellular hexokinase enzyme activity in response to infection with HIV-1." (PMID 29518929, 2018).
infection (continued). "The infection of human foreskin fibroblasts with DENV-2 resulted in increased glucose consumption and overexpression of GLUT1 as well as HK2." (PMID 29518929, 2018). "We therefore compared the expression levels of HK1, HK2, and VDAC in HIV-1 infected and uninfected CD4+ T cells at 24 and 48 h after infection." (PMID 29518929, 2018). "Active and VBNC infection of M0-BMDM induced a strong expression of these glycolytic genes at 24 h post-infection, and infection with HK + 1 induced the expression of Hk2, Pfkfb3, and Acod1." (PMID 39714095, 2025). "Furthermore, in the FMDV infection state, the ECAR in PK-15 cells decreased after 2-DG treatment but significantly increased after HK2 overexpression." (PMID 40170113, 2025). "Under hypoxic conditions, HIF-1 levels quickly increase and enhance cellular glycolytic capacity by transcriptionally upregulating key glycolytic genes, including HK2, Pfkfb, Pkm2, and Ldha, all of which were upregulated in murine spleens following PCN033 infection based on our transcriptomic data." (PMID 41295668, 2025). "Amongst genes regulated by infection with acidosis but not at pH 7.4 the Reactome gene set “glycolysis” was enriched and expression of glycolysis genes (HK2, ALDOC, LDHB) was increased by acidosis." (PMID 37418488, 2023). "We also showed a significantly reduced level of protein biosynthesis (mTOR signaling), lipid biosynthesis (SREBP signaling) and glucose uptake (AMPK activation) and glycolysis (HK2) in the lungs during infection in adult mice irrespective of diet." (PMID 35329973, 2022). "HK2 mRNA levels were significantly increased 4 hours post Stm infection in M2, but were not altered in Stm- or Mtb-infected M1." (PMID 34552598, 2021). "Senexin A did not entirely block HK2 induction by infection but did reduce it (2.88 ± 0.21-fold increase over mock vs. a 5.10 ± 0.49-fold increase in DMSO-treated infected cells)." (PMID 32560467, 2020). "In contrast, lonidamine, a reported hexokinase 2 (HK2) inhibitor, enhanced the infection and oncolytic effect of M1 virus independent of HK2." (PMID 33292203, 2020). "In this study, we showed that strain lacking HK2 reduced infectivity via tick bites, the nature route of infection." (PMID 33195322, 2020). "By contrast, HK2 was not significantly upregulated at 24 or 48 h after infection, as is consistent with our previous results." (PMID 29518929, 2018). "We observed that forced expression of cytoplasmic but not nuclear hnRNP A1 in cells with reduced levels of HK2 restored infection of HRV." (PMID 26247723, 2015). "Of the 17 HPK genes identified important for A/WSN/33 replication, six (CDK13, HK2, NEK8, PANK4, PLK4, SGK3) emulated the phenotype following A/New Caledonia/20/99 infection, i.e. increased or decreased virus replication as measured by influenza NP localization and influenza M gene levels." (PMID 23805279, 2013). "Notably, HIF-1α is important for neutrophil survival in normoxia as well as hypoxia, and VEGFA and many other HIF-1α target genes, but not HIF1A itself, are upregulated following LVS infection including HK2, LDHA, PDK1 and SCL2A1." (PMID 35873156, 2022). "Although HK2 is not required for mammalian infection via needle inoculation using in vitro cultured spirochetes, it remains to be determined whether HK2 plays a role via tick infestation." (PMID 33195322, 2020). "Previously it was shown that the cognate histidine kinase HK2 is not required for Rrp2 activation in vitro, nor for mammalian infection upon needle inoculation, raising the question whether HK2 has any role in the enzootic cycle of B. burgdorferi." (PMID 33195322, 2020). "When spirochetes migrate from ticks to the mammalian host, the Hk2-Rrp2 pathway is activated during tick feeding, leading to the production of OspC, DbpA/B, BBK32 BBA64 and many factors that are important for B. burgdorferi to establish infection in the mammalian host." (PMID 21738477, 2011).
infection (continued). "However, HK2 KO and HIF1A KO cells pretreated with TNFα fully restricted HCMV initiation of infection, indicating these factors are not necessary for TNFα’s anti-viral activity." (PMID 35834576, 2022). "We note that at late time points post-infection (48 h), with high virus titer, this upregulation was no longer detectable (GLUT1) or even reverted (HK2, LDH), which is expected as DENV, after 24 h of infection, is known to reduce cell viability and promote apoptosis." (PMID 30513781, 2018).
metabolic disorders (9 papers, 2013 to 2025). "In our study, ovarian HK1, HK2, PDHX and ACSS2 were repressed but FBP2 and ALDH1B1 were activated in DHT-treated rats, further complicating the metabolic disorders in those groups." (PMID 25887459, 2015). "Hexokinase 2 (HK2)-driven glycolysis induces lactate signaling, leading to histone lactylation, which further reinforces M1 gene expression in liver macrophages during metabolic disease." (PMID 41488672, 2025). "Aerobic glycolysis via HK2 in the placenta of patients with GDM may lead to HK2 expression upregulation due to reduced mitochondrial respiration, resulting in metabolic disorders in patients with GDM." (PMID 38234430, 2023).
colorectal (7 papers, 2015 to 2023). "In conclusion, our data shows that KCNQ1OT1 regulates colorectal carcinogenesis by upregualting aerobic glycolysis via HK2." (PMID 32564010, 2020). "In conclusion, our study demonstrates that high KCNQ1OT1 expression promotes colorectal carcinogenesis by enhancing aerobic glycolysis through direct binding and stabilization of hexokinase 2 (HK2)." (PMID 32564010, 2020). "To clarify the effect of HK2 on SCC, we conducted in vitro experiments with two lung ADC cell lines (A549 and PC9) and two lung SCC cell lines (H520 and H226) reported to have clear differences in HK2 expression." (PMID 32083006, 2020).
inflammation (6 papers, 2018 to 2025). Aberrant reaction of the microcirculation characterized by movement of fluid and leukocytes from the blood into extravascular tissues. "Similarly, in ventilator-induced lung inflammation, NETs facilitate M1 polarization by targeting hexokinase-2 (HK-2), further amplifying pulmonary inflammation." (PMID 40442839, 2025). "We also tested the necessity of HK2 in a mouse model of Th2 lung inflammation by sensitizing WT and T-Hk2−/− mice with ovalbumin/aluminum hydroxide (OVA/alum) and provoking airway inflammation subsequently with aerosolized OVA." (PMID 30140438, 2018). "On the contrary, HK2-CKO mice exhibited noticeably lower inflammatory (2.56 ± 0.08 vs. 1.64 ± 0.09, p < 0.0001), indicating that airway epithelial-specific knockdown of HK2 markedly attenuated OVA-induced airway inflammation." (PMID 40643524, 2025).
tumors of the digestive system (5 papers, 2017 to 2024). "GI tumor tissues with higher CBX3 K10la intensities exhibited elevated protein levels of hexokinase 2 (HK2), glucose‐6‐phosphate isomerase (GPI), and pyruvate kinase M (PKM)." (PMID 39018247, 2024). "Several previous studies have reported the prognostic value of hexokinase 2 (HK2) in digestive system tumors." (PMID 28415659, 2017).
adenocarcinoma (4 papers, 2013 to 2023). A common cancer characterized by the presence of malignant glandular cells. "One of the most common BAs, deoxycholic acid (DCA), was found to increase the HK2 expression and in turn the cellular glycolysis in adenocarcinoma cells." (PMID 36831193, 2023). "GLUT1 staining was seen in the cell walls, while HK2 staining was observed in the cytoplasm, of tubular (Figure 2a1, 2b1) and poorly differentiated (Figure 2a2, 2b2) adenocarcinomas." (PMID 23718763, 2013).
bacterial infection (2 papers, 2023). "The studies herein have identified the downstream ISGs TNRFSF10A, PML, MYD88, EHD4, and HK2 that potentiate secondary bacterial infection." (PMID 37939149, 2023). "Therefore, we next sought to determine whether the surge in HK2-mediated glycolysis in human gingival fibroblasts after bacterial infection was a result of HIF-1α activation." (PMID 36793034, 2023).